RNU6-1224P (RNA, U6 small nuclear 1224, pseudogene)
Gene: Small nuclear RNA gene on chromosome 8 (102,533,241 to 102,533,339, reverse strand). Ensembl gene ENSG00000252593.
Homologues: Orthologues: chimpanzee U6 (100% identical), macaque U6 (97% identical), guinea pig U6 (77% identical), pig U6 (76% identical). Paralogues in human: RNU6-1091P (82% identical), RNU6-1209P (82% identical), RNU6-1311P (82% identical), RNU6-1094P (81% identical), RNU6-1145P (81% identical), RNU6-1316P (81% identical), RNU6-28P (81% identical), RNU6-338P (81% identical), RNU6-560P (81% identical), RNU6-726P (81% identical), RNU6-778P (81% identical), RNU6-797P (81% identical), and 1288 more.